NLRP1 (NLR family pyrin domain containing 1)
Diseases named in the same sentence as NLRP1 in open-access papers (continued):
Sharing a sentence is not in itself a finding about the gene and the disease.
depression (continued). "Therefore, aging could be a key factor in the interplay of NLRP1 inflammasome and autophagy, and the precise mechanism under their interaction in depression deserves further investigation in the future." (PMID 38178196, 2024). "Unlike NLRP3, NLRP1 is mainly presented in neurons and dominantly implicated in neuronal injury pathologies and cognitive impairment, which is a core feature of subjects with depression." (PMID 32513185, 2020). "However, little is known about the role of NLRP1 inflammasome in depression." (PMID 32513185, 2020). "However, the interplay of NLRP1 inflammasome and autophagy in depression remains unclear." (PMID 38178196, 2024). "Thus, we surmise that the NLRP1 inflammasome may be a key target of Hyp in depression treatment." (PMID 36556951, 2022). "Thus, NLRP1 inflammasome could affect the levels of BDNF in stress-induced depression model." (PMID 32513185, 2020). "However, the definitive role of NLRP1 inflammasome in depression remains unclear." (PMID 32513185, 2020). "Therefore, we propose that NLRP1 inflammasome could play an important role in depression." (PMID 32513185, 2020). "Although our findings revealed the interaction between NLRP1 inflammasome and autophagy in CSDS-induced depression model, the underlying molecular mechanisms was not fully elucidated." (PMID 38178196, 2024). "Our data showed that stress stimuli significantly increased the protein expression of NLRP1, ASC, and caspase-1, and also markedly increased the mRNA levels of NLRP1, ASC, and caspase-1, indicating NLRP1 inflammasome was activated in stress-induced depression models." (PMID 32513185, 2020).
epilepsy (8 papers, 2015 to 2026). A brain disorder characterized by episodes of abnormally increased neuronal discharge resulting in transient episodes of sensory or motor neurological dysfunction, or psychic dysfunction. "In addition, other members of the NLR family, such as NLRP1, have previously been implicated in epilepsy and were found to contribute to neuronal death and chronic seizure activity in the amygdala kindling-induced rat model of epilepsy." (PMID 34220868, 2021). "Furthermore, NLRP1 inflammasome was also implicated in the processes of Alzheimer’s disease (AD), nociception, and epilepsy." (PMID 26715049, 2015). "In the amygdala-ignited rat epilepsy model, knockdown of NLRP1, NLRP3 and Caspase 1 genes by using siRNA technology also reduced epileptic activity." (PMID 40217546, 2025). "Laboratory studies from epilepsy have shown that the levels of inflammasomes (NLRP1, NLRP3, caspase 1, IL-1β, ASC, AIM2, gasdermin D, IL-18, intracellular calcium ion, sTNFr2) were also elevated." (PMID 40217546, 2025). "In particular, seizures were effectively controlled by decreasing the levels of AIM2 and NLRP3 and NLRP1 in a mouse model of kainic acid-induced epilepsy." (PMID 40217546, 2025). "NLRP1 inflammasome-driven inflammatory pathway has been reported to implicate in many neurological diseases such as brain injury, neurodegenerative diseases, nociception, and epilepsy." (PMID 32513185, 2020). "As the first discovered molecular platform, NLRP1 (nucleotide-binding oligomerization domain (NOD)-like receptor protein 1) inflammasome is expressed in neurons and implicated in many nervous system diseases such as brain injury, nociception and epilepsy." (PMID 26715049, 2015). "Recently, the expression of NLRP1 and NLRP3 mRNAs was significantly increased in the animal model of epilepsy induced by the intrahippocampal injection of KA compared to controls." (PMID 38892264, 2024). "Lines reported that the activation of NLRP1 and NLRP3 inflammasomes is involved in the development of epilepsy." (PMID 37365625, 2023). "NLRP1 and NLRP3 are the two best characterized members of inflammasomes and their activation during epilepsy has been documented in both basic and clinical researches." (PMID 28503575, 2017). "As the first identified inflammasome, NLRP1 inflammasome is expressed in neurons and involved in many nervous system diseases such as thromboembolic stroke, SCI, TBI, AD, nociception, and epilepsy." (PMID 26715049, 2015). "In the kainic acid epilepsy mouse model, the results of the three studies collectively point to the signaling pathways of NLRP1, NLRP3, absent in melanoma 2 (AIM2), caspase 1, and ASC playing a key role in the activation of inflammation during epilepsy." (PMID 40217546, 2025).
pancreatic cancer (8 papers, 2017 to 2025). "We also showed that the genes encoding proapoptotic proteins, namely DEDD2, DAPK3, and NLRP1, were overexpressed in pancreatic cancer cell lines treated with AbE." (PMID 30514293, 2018). "Conversely, diminished levels of NLRP1 increased the sensitivity of pancreatic cancer cells to ERK inhibitors." (PMID 40237399, 2025). "We also determined that the human ortholog NLRP1 is somatically altered in human pancreatic cancers by screening publicly available whole exome or whole genome sequencing data." (PMID 31780749, 2019). "In vitro, CCK8 and Transwell assay suggested that CASP4 may accelerate the progression of PDAC by promoting proliferation and migration of pancreatic cancer cells, while NLRP1 has been found to have tumor suppressive effect." (PMID 35633405, 2022). "Finally, we investigated the relationship between CASP4 and NLRP1 expression levels and drug sensitivity in pancreatic cancer cells." (PMID 35633405, 2022). "Finally, high expression of CASP4 and low expression of NLRP1 increased the sensitivity of pancreatic cancer cells to ERK inhibitors." (PMID 35633405, 2022). "Finally, to evaluate the risk and prognosis in pancreatic cancer more conveniently using pyroptosis-related genes, we constructed a prognostic model consisting of seven PRGs, including CASP4, GSDMC, NLRP1, PLCG1, IL-18, CASP1 and NLRP2." (PMID 35712482, 2022). "Collectively, our data not only suggest that disruption of the NLRP1 inflammasome plays a role in pancreatic cancer progression, but also indicate that disruption may occur by genetic mechanisms." (PMID 31780749, 2019). "In addition to pyroptosis, CASP4 may promote pancreatic cancer cell migration by promoting fatty acid synthesis, as well as NLRP1 was also closely related to the RAS/ERK signaling pathway." (PMID 35633405, 2022). "But it was the limitation of this study that we haven’t conducted experiments to investigate whether the expression of CASP4/NLRP1 influenced the sensitivity of pancreatic cancer to these drugs., such as comparing tumor growth by using MEK or AKT inhibitors in vivo with animals." (PMID 35633405, 2022). "A recent study predicted the prognosis of pancreatic cancer using a two-gene signature (CASP4 and NLRP1) based on genes related to pyroptosis." (PMID 38048216, 2023). "An additional risk model PRG based on more immune-related genes (CASP4, GSDMC, IL-18, NLRP1, NLRP2, PLCG1, TIRAP, and TNF) was developed, which can be used to predict pancreatic cancer prognosis with an accuracy of medium to high." (PMID 37893166, 2023). "According to this study, PRGs risk models were defined with the combination of immune and signaling pathways genes (CASP4, GSDMC, NLRP1, PLCG1, IL-18, CASP1, and NLRP2), among which CASP4, NLRP1, PLCG1, IL-18, and CASP1 are overexpressed in pancreatic cancers." (PMID 37893166, 2023).
asthma (7 papers, 2019 to 2025). "Using single-variant association testing they found that, as it was the case in the Brazilian cohort, the rs11651270 NLRP1 SNP was associated with asthma." (PMID 36189256, 2022). "In the same cohort, minor alleles of two of the NLRP1 SNPs (rs11651270/C and rs2670660/G) also showed an association to asthma severity and high levels of IgE." (PMID 36189256, 2022). "explored the relationship between NLRP1 and asthma in a Mexican American asthmatic children cohort to find that the NLRP1 2A haplotype was associated with asthma." (PMID 36189256, 2022). "Two NLRP1 variants, V1059M and M1184V, were associated with asthma status in our study; however, only 1 variant, M1184V, remained suggestively associated with asthma after correction for multiple testing (P = .02; Table E10, Table E11, Table E8, Table E9)." (PMID 33378691, 2021). "Collectively, this work defines the role of NLRP1 in asthma at a molecular level, and explains how the M1184V risk factor decreases activation in the context of DPP9 inhibition." (PMID 33378691, 2021). "Combined with the in vitro data, this aligns with a causative effect of M1184V in asthma to decrease NLRP1 activation in the context of DPP9 inhibition." (PMID 33378691, 2021). "In a discovery cohort of 905 Mexican American children with and without asthma from the GALA II study, we assessed the effect of select NLRP1 SNPs on asthma susceptibility." (PMID 33378691, 2021). "Here, we confirm that the M1184V mutation within the FIIND domain of NLRP1 is associated with increased asthma severity." (PMID 33378691, 2021). "We document the association of an NLRP1 haplotype with asthma for which the single nucleotide polymorphism rs11651270 (M1184V) individually is the most significant." (PMID 33378691, 2021). "Regression-based haplotype analysis revealed 1 NLRP1 haplotype significantly associated with asthma status, compared with the most common/reference haplotype (Table E10, Table E11, Table E8, Table E9)." (PMID 33378691, 2021). "Taken together these data provide evidence for an NLRP1 dependent IL18-mediated protective role in asthma, that could be disrupted by an altered NLRP1 activation related to polymorphisms such as rs11651270/C." (PMID 36189256, 2022). "In addition, genetic manipulation of Nlrp1 in mouse models of asthma shows that Nlrp1 deficiency exacerbates asthma models." (PMID 33378691, 2021). "Linking our in vitro and in vivo results, we found that the NLRP1 variant M1184V reduces inflammasome activation in the context of dipeptidyl peptidase 9 inhibition and could thereby increase asthma severity." (PMID 33378691, 2021). "Our studies may have implications for the treatment of asthma in patients carrying this variant of NLRP1." (PMID 33378691, 2021). "We then performed single-variant association testing, using logistic regression, to assess the impact of the 3 nonsynonymous NLRP1 polymorphisms in haplotype 2A—L155H (rs12150220), V1059M (rs2301582), and M1184V (rs11651270)—on asthma status in our study population." (PMID 33378691, 2021). "The results obtained from Nlrp1−/− mice suggest a protective effect of Nlrp1 activation in the asthma model." (PMID 33378691, 2021). "In vitro and in vivo models for NLRP1 activation were applied to investigate the role of this inflammasome in asthma at the molecular level." (PMID 33378691, 2021). "Results from the GALA II cohort study were used to identify a link between NLRP1 and asthma in Mexican Americans." (PMID 33378691, 2021). "A protective effect of Nlrp1 in the asthma model was also indicated by an increase in IL-13 in the BAL fluid of Nlrp1−/− mice." (PMID 33378691, 2021). "In contrast, our data to demonstrate that activation of Nlrp1 can prevent a model of asthma are consistent with results from a model of bleomycin-induced lung fibrosis." (PMID 33378691, 2021).
asthma (continued). "Furthermore, the NLRP1 deficient mice showed increased IL13 levels in BAL, suggesting a protective effect for NLRP1 in the context of asthma." (PMID 36189256, 2022). "Furthermore, the expression of canonical PRGs, such as GSDMB, caspase-4, and NLRP1, was upregulated in the poorly controlled asthma subtype." (PMID 35967302, 2022). "Therefore, we wanted to further investigate the role of the proinflammatory cytokines IL-1β and IL-18 in mediating protection during asthma, because both cytokines are released on Nlrp1 activation." (PMID 33378691, 2021). "Polymorphisms in NLRP1 are linked to asthma; however, there is currently no functional or mechanistic explanation for this." (PMID 33378691, 2021). "To better understand the role of Nlrp1 in asthma, we used an alum/ovalbumin (OVA) mouse model." (PMID 33378691, 2021). "We sought to clarify the role of NLRP1 in asthma pathogenesis." (PMID 33378691, 2021). "Interestingly, Nlrp1−/− mice showed increased eosinophilia compared with WT mice, suggesting a protective effect of NLRP1 in asthma." (PMID 33378691, 2021). "Although this variant does not cause hyperactivation of NLRP1 per se, as autoproteolysis itself is required but not sufficient for NLRP1 inflammasome activation, it has been associated with an increased risk of developing several autoimmune syndromes such as asthma or Crohn's disease." (PMID 36309085, 2022). "Nineteen differentially expressed PRGs were included in the mild-to-moderate and severe asthma samples, among which CAPN1, NLRP1, TRIM31, NOS2, and CDC37 showed the highest difference (P<0.01)." (PMID 35967302, 2022). "Il1r−/−/Neut1m/m mice exhibited decreased eosinophilia in the lung during asthma, indicating a protective effect of NLRP1 activity even in the absence of IL-1R." (PMID 33378691, 2021). "Using IL1R and IL18 deficient mice and the same asthma model, it was found that the potential protective effect of NLRP1 was not related to IL1R signaling, but to IL18 since IL1R but not IL18 deficient mouse, failed to reproduce the NLRP1 deficient phenotype." (PMID 36189256, 2022). "Because the protective effect of NLRP1 in asthma was independent of IL-1R signaling, we hypothesized that IL-18 plays a major role in mediating protection." (PMID 33378691, 2021).
glioma (7 papers, 2021 to 2024). A benign or malignant brain and spinal cord tumor that arises from glial cells (astrocytes, oligodendrocytes, ependymal cells). "The NLRP1 inflammasome is known to be positively associated with glioma in LGG and GBM, as demonstrated by in silico analysis." (PMID 37723542, 2023). "Particularly, high-grade glioma-associated microglia were observed to secrete IL-1β via the NLRP1 inflammasome, promoting tumor progression." (PMID 37749707, 2023). "In gliomas, knockdown of hsa_circ_0001836 significantly increased the expression of NLRP1, cleaved caspase-1 and GSDMD-N, and induced the pyroptosis of glioma cells." (PMID 36861130, 2023). "In terms of the function of the NLPR1 inflammasome in CNS disease, including glioma, the NLRP1 inflammasome in the hippocampus is positively correlated with neuroinflammation and neurofibrillary formation in Alzheimer’s disease (AD)." (PMID 37723542, 2023). "Most of these genes are risk factors for glioma, but NLRP1 and AIM2 have favorable effects on prognosis of glioma." (PMID 37501725, 2023). "Interestingly, in glioma or melanoma, TMZ-induced upregulation of NLRP1 and IL-1β is linked to the Notch1 signaling pathway and, subsequently, to the acquisition of drug resistance, as revealed by MAPK inhibitors." (PMID 37723542, 2023). "Furthermore, NLRP1 expression could affect immune cell infiltration in glioma, as observed through TIMER database analysis." (PMID 37723542, 2023).
inflammatory bowel disease (7 papers, 2018 to 2025). A spectrum of small and large bowel inflammatory diseases of unknown etiology. "Activation of inflammasomes particularly NLRP3 and NLRP1, plays central role in driving inflammatory response associated with inflammatory bowel disease (IBD)." (PMID 41129928, 2025). "Our data identify the NLRP1 inflammasome to be a key negative regulator of protective, butyrate-producing commensals, which therefore promotes inflammatory bowel disease." (PMID 30214011, 2018). "BB treatment significantly increased the relative abundance of unclassified Clostridiales, which produces butyrate and has been shown to inhibit NLRP1 inflammasome activation and prevent inflammatory bowel disease (IBD)." (PMID 34028176, 2021). "In addition, the NLRP1 inflammasome has been considered to be an important mediator, maintaining the host intestinal microbiota and controlling intestinal pathophysiology, as occurs in response to inflammatory bowel disease (IBD)." (PMID 34705319, 2021).
metastatic melanoma (7 papers, 2020 to 2025). A melanoma that has spread from its primary site to another anatomic site. "Mechanistic studies showed that cells employed NLRP1-dependent inflammasomes, and NLRP1 knockdown was associated with reduced activity of caspase-1, diminished secretion of IL-1β, and decreased activity of NF-κB in metastatic melanoma cells." (PMID 32340261, 2020). "In this paper, we demonstrated a novel mechanism of drug resistance where activated NLRP1 inflammasomes contribute to TMZ-induced acquired resistance in metastatic melanoma." (PMID 32899791, 2020). "Downregulation of NLRP1 promoted apoptosis in both primary and metastatic melanoma." (PMID 32340261, 2020). "In a study, NLRP1 operates as a downstream effector of MAPK/ERK signaling via activating transcription factor 4 (ATF4) in metastatic melanoma cells, where ATF4 directly regulates NLRP1." (PMID 40872623, 2025). "Here, we report that NLRP1 is a downstream effector of MAPK/ERK signaling through the activating transcription factor 4 (ATF4), creating regulation in metastatic melanoma cells." (PMID 33396632, 2020).
ovarian carcinoma (7 papers, 2019 to 2025). A malignant neoplasm originating from the surface ovarian epithelium. "At present, only two lncRNAs have been confirmed to regulate genes upstream of pyroptosis-related genes (NLRP1) in ovarian cancer." (PMID 35280739, 2022). "A recent study suggested that silencing of lncRNA HOTTIP results in the inhibition of cell proliferation and NLRP1 inflammasome-mediated pyroptosis in ovarian cancer." (PMID 35712671, 2022). "Through miRNA, these lncRNAs are connected with PRGs such as IRF1, NOD1, GSDMC, NLRP1, PLCG1, GSDME and GZMB to construct a pyroptosis related ceRNA regulatory network in ovarian cancer." (PMID 37859811, 2023). "Thus, we discovered many unproven pyroptosis related regulatory axes in ovarian cancer, such as KRT7-AS—has-miR-205—GSDMC, LINC01094—has-miR-330-3p—IRF1, ZNF32-AS2—has-miR-214—GSDME, and MYCNOS—has-miR-150—NLRP1." (PMID 37859811, 2023). "Additionally, in ovarian cancer, the silencing of HOTTIP led to NLRP1 inflammasome-mediated pyroptosis by focusing on miR-148a-3p/AKT2 axis as a target." (PMID 36281290, 2022). "As an upregulated lncRNA in ovarian cancer tissues and cell lines, HOTTIP silencing leads to NLRP1 inflammasome-mediated pyroptosis, decreases cell viability, increases the expression of pro-pyroptosis factors, like IL-18, IL-1β, and NLRP1, and activates caspase-1 in ovarian cancer cells." (PMID 39967908, 2025).